POLR3B (RNA polymerase III subunit B)
Description:
Catalytic core component of RNA polymerase III (Pol III), a DNA-dependent RNA polymerase which synthesizes small non-coding RNAs using the four ribonucleoside triphosphates as substrates. Synthesizes 5S rRNA, snRNAs, tRNAs and miRNAs from at least 500 distinct genomic loci. Pol III-mediated transcription cycle proceeds through transcription initiation, transcription elongation and transcription termination stages. During transcription initiation, Pol III is recruited to DNA promoters type I, II or III with the help of general transcription factors and other specific initiation factors. Once the polymerase has escaped from the promoter it enters the elongation phase during which RNA is actively polymerized, based on complementarity with the template DNA strand. Transcription termination involves the release of the RNA transcript and polymerase from the DNA. Forms Pol III active center together with the largest subunit POLR3A/RPC1. A single-stranded DNA template strand of the promoter is positioned within the central active site cleft of Pol III. Appends one nucleotide at a time to the 3' end of the nascent RNA, with POLR3A/RPC1 contributing a Mg(2+)-coordinating DxDGD motif, and POLR3B/RPC2 participating in the coordination of a second Mg(2+) ion and providing lysine residues believed to facilitate Watson-Crick base pairing between the incoming nucleotide and template base. Typically, Mg(2+) ions direct a 5' nucleoside triphosphate to form a phosphodiester bond with the 3' hydroxyl of the preceding nucleotide of the nascent RNA, with the elimination of pyrophosphate. Pol III plays a key role in sensing and limiting infection by intracellular bacteria and DNA viruses. Acts as a nuclear and cytosolic DNA sensor involved in innate immune response. Can sense non-self dsDNA that serves as template for transcription into dsRNA. The non-self RNA polymerase III transcripts, such as Epstein-Barr virus-encoded RNAs (EBERs) induce type I interferon and NF-kappa-B through the RIG-I pathway.
Synonyms: RPC2; FLJ10388; C128; CMT1I; HLD8; INMAP
Tractability: Small molecule: a structure with a bound ligand is known. PROTAC: ubiquitination databases record sites on it; its protein half-life has been measured.
Gene: Protein-coding gene on chromosome 12 (106,357,693 to 106,510,201, forward strand). Ensembl gene ENSG00000013503.
Subcellular location: Nucleus; Cytoplasm, cytosol
Subcellular location (Human Protein Atlas): Nuclear speckles
Pathways (Reactome):
Gene expression (Transcription): RNA Polymerase III Abortive And Retractive Initiation; RNA Polymerase III Chain Elongation; RNA Polymerase III Transcription Initiation From Type 1 Promoter; RNA Polymerase III Transcription Initiation From Type 2 Promoter; RNA Polymerase III Transcription Initiation From Type 3 Promoter; RNA Polymerase III Transcription Termination
Immune System: Cytosolic sensors of pathogen-associated DNA
Gene Ontology:
Molecular function: 5'-3' RNA polymerase activity; DNA-directed RNA polymerase activity; DNA/RNA hybrid binding; zinc ion binding; DNA binding; ribonucleoside binding
Biological process: positive regulation of innate immune response; positive regulation of interferon-beta production; snRNA transcription by RNA polymerase III; termination of RNA polymerase III transcription; transcription by RNA polymerase III; transcription initiation at RNA polymerase III promoter; DNA-templated transcription elongation; DNA-templated transcription
Cellular component: cytoplasm; nucleus; RNA polymerase III complex; cytosol; nucleoplasm; DNA-directed RNA polymerase complex; nuclear lumen
Genetic constraint (gnomAD): Loss-of-function variants: 60 observed, 88.51 expected, observed/expected ratio (o/e) 0.68, 90% interval 0.55 to 0.84. The upper end of that interval is the gene's LOEUF score, 0.84, which puts it in group 3 of 6, group 1 being the genes least tolerant of losing a copy. Missense variants: 744 observed, 1,054.8 expected, observed/expected ratio (o/e) 0.71, 90% interval 0.66 to 0.75. Synonymous variants: 333 observed, 370.68 expected, observed/expected ratio (o/e) 0.9, 90% interval 0.82 to 0.98.
Gene-disease validity (ClinGen):
ClinGen rates the evidence that POLR3B causes each of these diseases.
POLR3B-related disorder (autosomal dominant; autosomal recessive): Definitive. Disorder in which the cause of disease is a variation in the POLR3B gene.
Homologues: Orthologues: chimpanzee POLR3B (100% identical), macaque POLR3B (100% identical), dog POLR3B (99% identical), pig POLR3B (99% identical), mouse Polr3b (99% identical), rat Polr3b (99% identical), rabbit POLR3B (99% identical), guinea pig POLR3B (94% identical), tropical clawed frog polr3b (94% identical), zebrafish polr3b (94% identical), Drosophila melanogaster Polr3B (68% identical), Caenorhabditis elegans rpc-2 (64% identical). Paralogues in human: POLR2B (40% identical), POLR1B (30% identical).
Diseases named in the same sentence as POLR3B in open-access papers:
POLR3B is named in the same sentence as 39 diseases in open-access papers, as found by Europe PMC text mining. Sharing a sentence is not in itself a finding about the gene and the disease. The quoted sentences say what the papers report.
leukodystrophy (32 papers, 2015 to 2026). Leukodystrophies are a group of rare, progressive, metabolic, genetic diseases that affect the brain, spinal cord and often the peripheral nerves. "This article describes a rare variant of СНН as a result of pathogenic variants in the POLR3B gene, occurring in 1.1% of cases of СНН, which is a component of hypomyelinating leukodystrophy 4H and includes hypomyelination, CHН, hypodontia." (PMID 41640168, 2026). "Intriguingly, one patient with a heterozygous POLR3B variant was diagnosed with hypogonadotropic hypogonadism, which was described in 4H leukodystrophy (OMIM#614381) patients with biallelic variants in the same gene." (PMID 39776111, 2025). "Since we were interested in developing a leukodystrophy model based on a Polr3b mutation, it was important to make sure that the selected mutant impacted Pol III in a similar manner to patient-derived mutations." (PMID 37635302, 2023). "The clinical manifestations of disease in the model, including hypomyelination, hypodontia and craniofacial abnormalities, resemble those seen in patients with leukodystrophy caused by POLR3B mutations." (PMID 37635302, 2023). "In our experiments, riluzole treatment resulted in a positive impact on Pol III assembly in the leukodystrophy-causative POLR3B R103H model." (PMID 36451185, 2022). "In conclusion, the brother and the sister with new compound heterozygous variants in POLR3B had typical leukodystrophy symptom." (PMID 36042647, 2022). "POLR3A or POLR3B mutations cause the majority of POLR3-related leukodystrophy cases, with POLR1C mutations accounting for approximately 5% of cases." (PMID 35685919, 2022). "Mutations in POLR3A and POLR3B have been implicated in ID, which generally presents with 4H leukodystrophy." (PMID 35436926, 2022). "In this manuscript, we show that riluzole, an FDA-approved drug for the treatment of ALS, partially corrects Pol III assembly defects induced by the leukodystrophy-causative amino acid substitution R103H in POLR3B." (PMID 36451185, 2022). "Biallelic mutations in POLR3B are the well-established cause of hypomyelinating leukodystrophy, which is characterized by hypomyelination, hypodontia, and hypogonadotropic hypogonadism." (PMID 34666706, 2021). "Biallelic mutations in POLR3B are the well-established cause of hypomyelinating leukodystrophy, typically featured by hypomyelination, hypodontia, and hypogonadotropic hypogonadism." (PMID 34666706, 2021). "A second mouse model carrying the POLR3B leukodystrophy-mediating mutation p.R103H, which led to impaired Pol III assembly in human cultured cell lines, was embryonic lethal in homozygotes." (PMID 32611613, 2020). "To determine if other POLR3-HLD mutations can cause a leukodystrophy phenotype in mouse, we characterized mice carrying the Polr3b mutation c.308G > A (p.Arg103His)." (PMID 31221184, 2019). "4H syndrome is a congenital hypomyelinating leukodystrophy characterized by hypodontia, hypomyelination and hypogonadotropic hypogonadism belonging to the Pol III-related leukodystrophies which arise due to mutations in the POLR3A or POLR3B gene." (PMID 29618326, 2018). "The mutations in POLR3A and POLR3B are the most frequently reported etiology for 4H leukodystrophy." (PMID 36042647, 2022). "Most interestingly, we show that treatment with riluzole, an FDA-approved drug for amyotrophic lateral sclerosis (ALS) treatment, partly corrects the defects in Pol III assembly in the presence of a POLR3B subunit having the R103H substitution known to be causative for POLR3-related leukodystrophy." (PMID 36451185, 2022). "However, an interaction was found between riluzole treatment and cells expressing the leukodystrophy-related variant POLR3B R103H and this treatment stimulates Pol III assembly." (PMID 36451185, 2022).
leukodystrophy (continued). "In addition to a mutation in exon 15 of the POLR3B gene, which is relatively common amongst patients with 4H leukodystrophy caused by POLR3B mutations, our patient also has a unique intronic mutation at intron 24, which has not been described in others with 4H leukodystrophy." (PMID 26113998, 2015). "This case series describes two siblings from a consanguineous family with genetically confirmed POLR3B-related leukodystrophy, highlighting intrafamilial phenotypic variability and underscoring the need for coordinated multidisciplinary management." (PMID 40978896, 2025). "In the last few years, our group has identified and validated eight genes causative for leukodystrophy, including POLR3A, POLR3B, POLR1C, POLR3D, EPRS1, VARS1, and ABHD16A." (PMID 39062571, 2024). "Recently, a multicenter retrospective study including 150 patients with 4H leukodystrophy demonstrated that 56 (37.3%) patients carried the mutations in POLR3A, 81 (54%) in POLR3B, and 13 (8.7%) in POLR1C." (PMID 36042647, 2022). "POLR3-related leukodystrophy is caused by biallelic pathogenic variants in genes encoding subunits of Pol III, i.e. POLR3A, POLR3B, POLR1C and POLR3K." (PMID 36451185, 2022). "A total of 150 patients with 4H leukodystrophy and pathogenic variants in POLR3A, POLR3B, or POLR1C were included." (PMID 33005949, 2021). "4H leukodystrophy has been found to be caused by biallelic pathogenic variants in POLR3A, POLR3B, POLR1C, and POLR3K, each of which encode subunits of the POLR3 complex." (PMID 33005949, 2021). "POLR3-related leukodystrophy is caused by biallelic mutations in POLR3A, POLR3B, POLR1C, and POLR3K (through interaction with POLR3B) genes." (PMID 31438894, 2019). "Recessive mutations in the ubiquitously expressed POLR3A and POLR3B genes are the most common cause of POLR3-related hypomyelinating leukodystrophy (POLR3-HLD), a rare childhood-onset disorder characterized by deficient cerebral myelin formation and cerebellar atrophy." (PMID 31221184, 2019). "4H syndrome is a rare congenital hypomyelinating leukodystrophy inherited as an autosomal recessive disorder due to mutations in the POLR3A and POLR3B gene." (PMID 29618326, 2018). "Pol III-related leukodystrophies are inherited in an autosomal recessive manner and result from mutations in POLR3A gene on chromosome 10q22 or the POLR3B genes on chromosome 12q23." (PMID 29618326, 2018). "Mutations in POLR3A and POLR3B, which encode the two largest subunits of RNA polymerase III (Pol III), have now been identified in several patients with 4H leukodystrophy." (PMID 26113998, 2015). "While approximately half of all patients carry mutations in POLR3B encoding the RNA polymerase III subunit B, there is no in vivo model of leukodystrophy based on mutation of this Pol III subunit." (PMID 37635302, 2023). "Nearly half of the patients with POLR3-HLD carry mutations in POLR3B and there is no working model of leukodystrophy based on that gene, so we elected to use Polr3b for our murine model." (PMID 37635302, 2023). "Their interaction occurred early and was not affected by the leukodystrophy-associated substitution R103H in POLR3B." (PMID 36451185, 2022). "4H or POLR3-related leukodystrophy is an autosomal recessive disorder typically characterized by hypomyelination, hypodontia, and hypogonadotropic hypogonadism, caused by biallelic pathogenic variants in POLR3A, POLR3B, POLR1C, and POLR3K." (PMID 33005949, 2021). "Mutations in genes encoding subunits of the transcription complex RNA polymerase III (POLR3), namely POLR3A, POLR3B, POLR1C, POLR3K and POLR3GL might cause a particular type of hypomyelinating leukodystrophies known as Pol III-related leukodystrophies." (PMID 33804237, 2021). "In addition, an ever-increasing number of distinct mutations in the POLR3A, POLR3B, POLR1C and POLR3K subunits cause a spectrum of neurodegenerative diseases, which includes most notably hypomyelinating leukodystrophy." (PMID 34395528, 2021).
leukodystrophy (continued). "A recent study reported six unrelated patients carrying heterozygous de novo variants in POLR3B manifested ataxia, developmental delay, spasticity and demyelinating neuropathy, which differed from previously reported phenotypes of POLR3B-related hypomyelinating leukodystrophy." (PMID 34666706, 2021). "Severe myopia, which occurs very frequently in children with 4H leukodystrophy and especially POLR3B variants, was not present." (PMID 31940116, 2020). "4H or POLR3-related leukodystrophy is inherited in an autosomal recessive fashion and is caused by mutations in one of three genes encoding RNA polymerase III (POLR3) subunits, that is, POLR3A, POLR3B, and POLR1C." (PMID 26478204, 2017). "To investigate the genetic aetiology of these unexplained cases, we performed exome sequencing in three cases with typical clinical and/or radiological features of POLR3-related leukodystrophy negative for POLR3A or POLR3B mutation." (PMID 26151409, 2015). "POLR3-related (or 4H) leukodystrophy is an autosomal recessive disorder caused by mutations in POLR3A or POLR3B and is characterized by neurological and non-neurological features." (PMID 26045207, 2015). "These are the first reports of long deletions causing POLR3-related leukodystrophy, suggesting that deletions and duplications in POLR3A or POLR3B should be investigated in patients with a compatible phenotype, especially if one pathogenic variant has been identified." (PMID 26045207, 2015). "A subset of patients (∼5%) presenting with compatible clinical and/or radiological features of POLR3-related leukodystrophy have no detectible mutations in either POLR3A or POLR3B, suggesting that mutations in one or more additional genes may result in this presentation." (PMID 26151409, 2015). "The patient was firstly diagnosed as an undefined hypomyelination leukodystrophy and reached the final genetically confirmed diagnosis ten years later, following the description of POLR3A and POLR3B as disease genes." (PMID 26204956, 2015). "POLR3-HLD, also termed 4H (Hypomyelination, Hypodontia, and Hypogonadotropic Hypogonadism) leukodystrophy, is caused by biallelic pathogenic variants in genes encoding subunits of the ubiquitous RNA polymerase III (Pol III) enzymatic complex (e.g., POLR3A, POLR3B, POLR1C, POLR3K, and POLR3D)." (PMID 39062571, 2024). "However, since subtle PMG may be difficult to detect on MRI, it needs meticulous reading and is better seen with MRI protocols not typically performed in leukodystrophy patients, it is not possible to completely rule out that mutations in POLR3B are also causative for the PMG." (PMID 26478204, 2017). "Our assessment of the precursor stage suggested migration was unaffected when Polr3a, Polr3b, or Polr1c were downregulated, proposing that failure of OPCs to migrate to myelination sites is unlikely to explain the hypomyelination seen in POLR3-related leukodystrophy." (PMID 37179550, 2023).
hypogonadotropic hypogonadism (13 papers, 2015 to 2026). Abnormal ovarian or testicular function due to insufficient hormonal stimulation from the hypothalamic-pituitary axis. "For example, POLR3B has been associated with both Charcot–Marie–Tooth disease and syndromic hypogonadotropic hypogonadism." (PMID 38822427, 2024). "POLR3A and POLR3B can be also associated to neurological or dental anomalies and isolated hypogonadotropic hypogonadism." (PMID 32982993, 2020). "Considering hypogonadotropic hypogonadism caused by biallelic variants in POLR3B, serum reproductive hormone levels, including testosterone (TST), follicle stimulating hormone (FSH), luteinizing hormone (LH), estradiol (E2) and progesterone (PRG), were detected and were within normal range." (PMID 34666706, 2021). "Among them, 4H syndrome (hypomyelination, hypodontia, and hypogonadotropic hypogonadism) is a clinically and genetically heterogeneous disorder, primarily caused by mutations in POLR3A, POLR3B, and, more recently, POLR1C genes." (PMID 40978896, 2025). "We present a case series of two siblings from a consanguineous family with genetically confirmed POLR3B-related hypomyelinating leukodystrophy type 8 (4H syndrome), a rare autosomal recessive disorder characterized by hypomyelination, hypodontia, and hypogonadotropic hypogonadism." (PMID 40978896, 2025).
Cerebellar atrophy (6 papers, 2015 to 2024). Cerebellar atrophy is defined as a cerebellum with initially normal structures, in a posterior fossa with normal size, which displays enlarged fissures (interfolial spaces) in comparison to the foliae secondary to loss of tissue. "Cerebellar atrophy was found almost in all patients with 4H syndrome, but the cerebellar anomalies were more severe in patients with POLR3B while the pattern of hypomyelinization was more evident in the MRI of POLR3A mutated patients." (PMID 26204956, 2015). "When patients have corresponding symptoms or signs, and there are diffuse hypomyelination and cerebellar atrophy on craniocerebral imaging, clinicians should highly doubt the possibility of POLR3-HLD and consider the sequencing of POLR3A and POLR3B genes in time." (PMID 38561452, 2024).
Ataxia (5 papers, 2017 to 2025). Ataxia refers to impaired coordination of voluntary muscle movement. "Mutations in POLR3B are reported to cause hypomyelinating leukodystrophy type 8 and the clinical presentations of these mutations are widespread and include ataxia, spasticity, variable intellectual disability and epilepsy, and demyelinating sensory motor peripheral neuropathy." (PMID 34389898, 2021). "Currently, POLR3A, POLR3B, OTUD4, STUB1, PNPLA6, and RNF216 are all genes associated with CHH syndromes and cerebellar ataxia, with clinical manifestations that can vary and may present with infant or adult onset." (PMID 40508017, 2025).
myopia (4 papers, 2018 to 2024). "The frequency of myopia in our cohort was lower than that in previously reported patients with POLR3A or POLR3B variants (87%) (P < 0.001)." (PMID 38550343, 2024). "The frequency of myopia in our cohort was lower than that in previously reported patients with POLR3A or POLR3B variants." (PMID 38550343, 2024).
developmental delay (3 papers, 2017 to 2026). "The POLR3B (12q23.3, OMIM#614366) gene abnormality, observed in Patient 54, with early developmental delay, intellectual disability, ADHD and EMAtS, is consistent with previous descriptions but epitomizes the nosological limits of the EMAtS definition." (PMID 41523187, 2026).
Alzheimer disease (2 papers, 2015 to 2020). A progressive, neurodegenerative disease characterized by loss of function and death of nerve cells in several areas of the brain leading to loss of cognitive function such as memory and language. "Besides, POLR3B was reported to disturb the purine metabolism and contribute to Alzheimer’s disease." (PMID 25895500, 2015).